PIF1 (PIF1 5'-to-3' DNA helicase)
Diseases named in the same sentence as PIF1 in open-access papers (continued):
Sharing a sentence is not in itself a finding about the gene and the disease.
cancer (20 papers, 2012 to 2025). A tumor composed of atypical neoplastic, often pleomorphic cells that invade other tissues. "In a sub-set of these cancers, high PIF1 expression levels are also associated with poor patient survival." (PMID 39417423, 2024). "Notably, PIF1 mutations were rare in most cancer entities (<3% of tumour samples), despite the large sample sizes." (PMID 39417423, 2024). "Furthermore, PIF1 is rarely mutated in cancer, possibly underscoring its essential role in coping with replication stress during oncogenesis." (PMID 39417423, 2024). "Notably, the clinical genetics and disease association analysis of 33 different cancer entities showed that PIF1 expression is significantly higher in many cancers, indicating a role in tumorigenesis." (PMID 39417423, 2024). "However, Pif1 is related to cancer in humans since mutations in Pif1 have been linked to oncogenesis." (PMID 36838444, 2023). "A loss of Pif1 is known to result in longer telomeres in a telomerase-dependent manner, which could be a factor in the increased risk of cancer from a point mutation in hPIF1." (PMID 35409096, 2022). "While the mutation of the signature motif of Pif1 results in a phenotype leading to a higher risk of cancer, many studies indicate that the depletion of Pif1 also results in higher genomic instability and mutations that could lead to cancer." (PMID 35409096, 2022). "The L319P mutation in the helicase PIF1 is associated with cancer." (PMID 34139671, 2021). "Consistent with this view, mutations in human PIF1 are associated with increased cancer risk." (PMID 28475600, 2017). "Finally, we quantified the PIF1 mutation rate across various cancer types." (PMID 39417423, 2024). "First, we compared PIF1 mRNA expression between tumour and adjacent healthy tissues in each cancer type, when expression data for healthy tissue was available." (PMID 39417423, 2024). "In this study, we confirmed the differential expression of PIF1 in different types of store cancers based on pancancer analysis." (PMID 36685888, 2022). "By increasing ROS production, cancer cells and drug resistance can be eliminated, which has been demonstrated by a large number of FDA-approved anticancer drugs, while PIF1 is involved in reducing the mitochondrial DNA damage caused by ROS." (PMID 34608398, 2021). "The functions of human PIF1 (hPIF1) are also critical for survival of certain tumour cell lines during replication stress, making it an important target for cancer therapy." (PMID 30698796, 2019). "Since patient survival analysis is dependent on analysing the expression level of the gene of interest, tumour samples were categorized in to low- and high-PIF1 expression groups, individually for each of the 33 TCGA cancer cohorts, and Kaplan-Meier analyses were performed." (PMID 39417423, 2024). "A lack of correlation between PIF1 expression and patient survival in some cancer types is potentially linked to mutational and therapeutic backgrounds." (PMID 39417423, 2024). "Moreover, a Pan-cancer analysis of the TCGA database showed that PIF1 was highly expressed in most tumors compared to the normal tissue." (PMID 38086789, 2023). "It will be interesting to investigate if inhibition of the Pif1 helicase in mammalian cells has a similar CIN suppression effect that may be exploited for cancer prevention or treatment." (PMID 36350688, 2023). "All these results demonstrated that PIF1 might be a potential molecular biomarker for cancer diagnosis or a novel target for cancer therapy." (PMID 36685888, 2022). "As a result, the data suggest that PIF1 mRNA is abnormally expressed in various types of cancers." (PMID 36685888, 2022). "We evaluated the mRNA expression pattern of PIF1 in thirty-three types of cancer." (PMID 36685888, 2022).
cancer (continued). "Dna2, checkpoint proteins, Pif1 and Mph1 helicases, and Pol32 are all conserved between human and yeast cells, and affect telomere-related human diseases such as cancer, suggesting our observations may be relevant to human disease." (PMID 29559500, 2018). "Given that oncogenes induce high levels of replication stress during the early stages of tumorigenesis, this function of PIF1 could become critical during cancer development." (PMID 25359767, 2014). "We reasoned that PIF1 could affect DNA replication in a way that becomes particularly critical only during replication stress experienced by cancer cells." (PMID 25359767, 2014). "Significantly, PIF1 knock-out mice are normal and PIF1 expression very low in differentiated tissues, arguing for a non-essential role of PIF1 in non-proliferating human cells, so hPIF1 depletion may be less toxic to normal cells compared to cancer cells." (PMID 39417423, 2024). "Since not only PIF1 expression, but also other clinicopathological variables can affect patient survival, we performed a multivariate CoxPH model analysis to evaluate the independence of PIF1 expression as a prognostic factor, again considering all the 33 TCGA cancer cohorts." (PMID 39417423, 2024). "Therefore, PIF1 overexpression in ccRCC may curb tumor immune responses involved in immune escape, further promoting cancer growth." (PMID 36685888, 2022). "Therefore, some scholars have suggested that PIF1 is an important target in cancer treatment." (PMID 36685888, 2022). "Further, as demonstrated recently, the loss of the BIR factor PIF-1 can be exploited for selective killing of cells made to rely on this HR subpathway by the concurrent deletion of FANCM, revealing a new synthetic lethality relationship and an approach to target PIF-1 mutant cancer cells." (PMID 34408777, 2021). "Among the cancer driver genes that experienced epigenetic changes in at least five cancer types, we identified eight genes: CEP55, PIF1, RRM2, NCAPH, ZEB2, CIT, FLI1, and PCDH17." (PMID 31900418, 2020). "In support of this, reciprocal immunoprecipitation of C-terminal-FLAG-tagged PIF1 and endogenous CDC45 in human cancer cells has been reported, suggesting that PIF1 associates with the essential replication initiation co-factor CDC45 in vivo." (PMID 25359767, 2014). "Elevated expression of the DNA helicase genes BLM, PIF1, and RECQL4 which is generally observed in cancers may explain a recovery function from chromatin instability in ST2." (PMID 25460179, 2014). "To assess further the potential of PIF1 as a therapeutic target in cancer we interrogated clinical datasets from The Cancer Genome Atlas (TGCA) database, an extensive resource of 33 different cancer types, sequenced, molecularly characterized and matched to normal tissue." (PMID 39417423, 2024). "To date, the functions of PIF1 in cancer have not been studied and reported systematically." (PMID 36685888, 2022). "This work provides crucial evidence suggesting that not only is the role of Pif1 in BIR is likely to be broadly conserved among eukaryotes, but also providing a direct indication that BIR (and Pif1) may play roles in human genome integrity and cancers." (PMID 34573298, 2021).
tumor (12 papers, 2012 to 2025). "We performed a comprehensive evaluation of PIF1 expression in tumours and its association with patient outcome, using genomic, transcriptomic and clinical data." (PMID 39417423, 2024). "Targeting PIF1 by chemical inhibition or genetic modification in BRCA2-deficient MBs could allow for selective killing of tumor cells, sparing surrounding normal cerebellum that lacks Pif1 expression." (PMID 40854122, 2025). "PIF1 loss led to decreased replication speed in otherwise unperturbed primary tumor cells, indicating that loss or inhibition of this helicase may stall replication forks at lesions such as G4s and could reduce proliferation of tumor cells." (PMID 40854122, 2025). "The G4-unwinding PIF1 helicase was found to be upregulated in tumor cells as a potential way to cope with G4-related replication stress." (PMID 40854122, 2025). "RNAseq from samples serially harvested across tumor development, by sorting EdU-pulsed cells from the adult, postmitotic cerebellum at P35, P50, and P75, revealed that Pif1 upregulation occurred as early as P35, which coincided with early tumor development." (PMID 40854122, 2025). "The differential expression analysis between tumour and matched healthy tissue indicates that PIF1 expression is increased during the malignant transformation process." (PMID 39417423, 2024). "Human PIF1 (hPIF1) is poorly understood, but its functions can become critical for tumour cell survival during oncogene-driven replication stress." (PMID 39417423, 2024). "Overall, our findings indicate that hPIF1 plays a significant role in malignant transformation in some tumour types, with high PIF1 expression levels promoting tumour development and disease progression." (PMID 39417423, 2024). "We inferred the possibility that the attenuated tumor growth in PIF1-silenced group was due to elevated apoptosis and DNA damage." (PMID 38086789, 2023). "The deletion of PIF1 can inhibit entry into S-phase upon release from thymidine-induced replication arrest and delay the progression of S-phase in human tumor cells." (PMID 36685888, 2022). "Nonetheless, our results confirm the role of the circNEIL3/miR-1184/PIF1 axis in both tumor cells and subcutaneous tumors in mediating pyroptosis to regulate LUAD radiotherapy by regulating the DNA damage repair pathway." (PMID 35190532, 2022). "A few studies have reported that PIF1 was essential for human tumor cell proliferation, including HCT116 cells, HeLa cells, and HEY cells." (PMID 34608398, 2021). "Based on the hypersensitivity of PIF1-depleted tumour cells and RAS transformed fibroblasts to such inhibitors, we next investigated the potential role of PIF1 on recovery of DNA replication." (PMID 25359767, 2014). "Together with PIF1 expression, we considered age, gender, race, tumour stage and purity as variables that could affect survival time." (PMID 39417423, 2024). "Tumors isolated at the endpoint of the study showed significant reduction in tumor weight in the PIF1-silenced group treated with irradiation, indicating that inhibition of PIF1 could also enhance the radiosensitivity of NSCLC in vivo." (PMID 38086789, 2023). "Correlation analysis showed that PIF1-mediated carcinogenesis may participate in the process of tumor immune escape in ccRCC." (PMID 36685888, 2022). "Research shows that PIF1 plays a crucial role in the survival of human tumor cells, especially during replication stress, but this effect is not obvious in non-tumor cells and Pif1-deficient mice." (PMID 36685888, 2022). "PIF1 acts as a tumor promoter in CC via suppressing the TERT." (PMID 34181336, 2021). "Human PIF1 is essential for tumour cell viability, particularly during replication stress, but is dispensable in non-cancerous cells and Pif1 deficient mice." (PMID 25359767, 2014). "We present both genetic and functional data which suggests that PIF1 may function as a tumor suppressor." (PMID 22347400, 2012).
tumor (continued). "Thus, in the CoxPH analysis, elevated PIF1 expression is an indicator of worse survival in most of the tumour types significant in the Kaplan–Meier analysis, plus some additional types when PIF1 expression is considered alongside other clinico-pathological variables." (PMID 39417423, 2024). "PIF1 may play a distinct role in the microenvironment of ccRCC by regulating the tumor infiltration of immune cells, which is a new therapeutic target to affect the growth of the tumor." (PMID 36685888, 2022). "PIF1 may play a distinct role in the microenvironment of ccRCC by regulating tumor infiltration of immune cells, which is a new therapeutic target to affect the growth of the tumor." (PMID 36685888, 2022). "Moreover, our results of sensitisation of RAS transformed cells to gemcitabine upon PIF1 depletion warrant further studies of the effects of manipulation of PIF1 alone, as well as in combination with replication inhibitors or G4-ligands, on the survival of oncogene-driven tumours in model organisms." (PMID 25359767, 2014). "Slower fork rates were also detected in HCT116 tumour cells (with an activating K-RASG13D mutation) following PIF1-depletion [average fork rate: 0.58kb/min vs 0.74kb/min (p=0.046) for CIdU tracks and 0.49kb/min vs 0.58kb/min (p=0.041) for IdU tracks in PIF1 and control siRNA treated HCT116 cells]." (PMID 25359767, 2014). "We found that Pif1 was expressed both in tumor cells and proliferating GCPs but was not expressed in the normal adult cerebellum." (PMID 40854122, 2025). "In vivo studies, PIF1 was related to the essential replication initiation cofactor CDC45, and the interaction of endogenous CDC45 and C-terminal-FLAG-tagged PIF1 in human tumor cells was confirmed by coimmunoprecipitation." (PMID 36685888, 2022). "Immunohistochemistry analysis of tumor xenograft samples suggested that in the radiation-treated group, circNEIL3 knockdown elevated the expression of γH2AX, AIM2, cleaved caspase-1, and GSDMD, but reduced the levels of PIF1 and BRCA1." (PMID 35190532, 2022).
infection (2 papers, 2013 to 2024). The state of being infected such as from the introduction of a foreign agent such as serum, vaccine, antigenic substance or organism. "Some characteristics of the new virus are similar to AmFV, like the presence of the Baculoviridae-related regions (pif-1/2/3), which are important for cell entry and are essential for per os infection." (PMID 38441971, 2024). "In particular, lef-4, lef-5, lef-8, lef-9, and p47 are important for transcription, whereas pif-1-3, pif-4/19 kDa, and p74 are necessary for infection." (PMID 38441971, 2024). "Second, a shift in the frequencies of pif1 reprogrammed and deletion genotypes in mixed infections would be required to restore OB potency to that of the wild-type population." (PMID 24223853, 2013). "Temporal regulation of pif1 transcription was examined by quantitative RT-PCR (qRT-PCR) using total RNA isolated from infected S. frugiperda larvae at different times post-infection." (PMID 24223853, 2013). "The resulting accumulation of PIF1 in ODVs may have influenced the functionality or integrity of the complex of PIF factors required for ODV infectivity during primary infection." (PMID 24223853, 2013). "Modifying pif1 expression might affect the temporal expression of other genes that are directly or indirectly related to BV production, such as observed in another NPV gene, or may modify the course of the infection." (PMID 24223853, 2013).
genetic disorders (1 paper, 2021). "While we have placed our emphasis on the S. cerevisiae proteins Srs2 and Pif1, mutations in both Sf1a and Sf1b helicases in humans can lead to genetic disorders, and mutations in the yeast proteins may reflect these disorders." (PMID 34573298, 2021).
myopathy (1 paper, 2023). A disease of the muscle in which the muscle fibers do not function properly. "It appears that Pif1 functions in higher eukaryotes are more subtle than in yeast since mouse knocked–out for Pif1 are still viable and exhibit only phenotypes related to myopathy." (PMID 36838444, 2023).
PIF1 also shares sentences with these, for which no sentence is quoted: pancreatic cancer (2 papers); anemia (1); atherosclerosis (1); brain disorder (1); cervical squamous cell carcinoma (1); cholangiocarcinoma (1); endocervical adenocarcinoma (1); Hyperglycemia (1); Insulin resistance (1); mesothelioma (1); non-small cell lung carcinoma (1); sarcoma (1); steatosis (1); stomach adenocarcinoma (1); testicular germ cell tumor (1); uveal melanoma (1); Werner syndrome (1).